IGLV2-33 (immunoglobulin lambda variable 2-33 (non-functional))
Description:
Probable non-functional open reading frame (ORF) of V region of the variable domain of immunoglobulin light chains. Non-functional ORF generally cannot participate in the synthesis of a productive immunoglobulin chain due to altered V- (D)-J or switch recombination and/or splicing site (at mRNA level) and/or conserved amino acid change (protein level). Immunoglobulins, also known as antibodies, are membrane-bound or secreted glycoproteins produced by B lymphocytes. In the recognition phase of humoral immunity, the membrane-bound immunoglobulins serve as receptors which, upon binding of a specific antigen, trigger the clonal expansion and differentiation of B lymphocytes into immunoglobulins-secreting plasma cells. Secreted immunoglobulins mediate the effector phase of humoral immunity, which results in the elimination of bound antigens. The antigen binding site is formed by the variable domain of one heavy chain, together with that of its associated light chain. Thus, each immunoglobulin has two antigen binding sites with remarkable affinity for a particular antigen. The variable domains are assembled by a process called V-(D)-J rearrangement and can then be subjected to somatic hypermutations which, after exposure to antigen and selection, allow affinity maturation for a particular antigen.
Synonyms: IGLV233; V1-9
Gene: Immunoglobulin variable (V) gene on chromosome 22 (22,588,155 to 22,588,688, forward strand). Ensembl gene ENSG00000211656.
Subcellular location: Secreted; Cell membrane
Gene Ontology:
Biological process: immune response
Cellular component: extracellular region; immunoglobulin complex; plasma membrane
Homologues: Paralogues in human: IGLV2-18 (76% identical), IGLV2-11 (72% identical), IGLV2-14 (72% identical), IGLV2-8 (71% identical), IGLV2-23 (67% identical), IGLV1-40 (64% identical), IGLV1-50 (62% identical), IGLV1-44 (59% identical), IGLV1-47 (59% identical), IGLV1-51 (58% identical), IGLV1-36 (57% identical), IGLV6-57 (55% identical), and 81 more.